KRAS (KRas proto-oncogene, GTPase)
Diseases named in the same sentence as KRAS in open-access papers (continued):
Sharing a sentence is not in itself a finding about the gene and the disease.
lung cancer (continued). "In lung cancer, KRAS, MYC, EGFR, and ERBB family are well-known oncogenes, and all of them were found to be highly significant in copy number gains." (PMID 21829676, 2011). "KRAS and EGFR mutation status has been analyzed in primary tumors in the majority of the current studies, but it has been demonstrated that lung cancers are often heterogeneous at the molecular level, even within the same tumor." (PMID 21414214, 2011). "Let-7 family members are down-regulated in lung cancer cells which possibly increases cell growth by increasing KRAS levels." (PMID 21453501, 2011). "In this study, we utilized a GEPR for erlotinib, an EGFR-TKI, which was generated in lung cancer cell lines, to test its predictive capacity in KRAS-wildtype mCRC patients treated with the anti-EGFR mAB cetuximab." (PMID 19439077, 2009). "In a recent paper dealing with expression profiling of epidermal growth factor receptor/KRAS pathway activation in lung cancer two groups of ADC were individualized, one being a bronchial-type, the other an alveolar-type." (PMID 18549475, 2008). "Given that KRAS acts upstream of AKT and is frequently mutated in lung cancer, combined targeting of KRAS and ZC3H15 may represent a promising therapeutic approach." (PMID 41513632, 2026). "Interestingly, long-term trametinib treatment (10 days) resulted in a rebound in ERK phosphorylation and further upregulation of AKT phosphorylation, suggesting rapid adaptive resistance to MEK inhibitors in KRAS-mutant lung cancer." (PMID 40935839, 2025). "SLC7A11, another glutamate antiporter, is required for KRAS-mutant driven lung cancer." (PMID 39806421, 2025). "This approach may have overestimated the sensitivity and specificity of radiomics models in distinguishing the KRAS status in lung cancer." (PMID 41584578, 2025). "Consequently, there remains an urgent and pressing need to decipher the molecular mechanisms driving KRAS-driven lung cancer progression and to explore alternative therapeutic strategies." (PMID 40885716, 2025). "For example, a custom siRNA, EFTX-D1, has shown specificity in suppressing the expression of KRAS mutations in codon 12 and codon 13 without affecting WT KRAS in various lung cancer cell lines." (PMID 39820726, 2025). "KRAS mutants confer NSCLC drug resistance in primary lung cancer cells from patients." (PMID 39960727, 2025). "In addition, the m6A methylation levels of DDB2 and XPC transcripts were also higher in primary KRAS-mutant lung cancer cells compared with primary KRAS WT lung cancer cells." (PMID 39960727, 2025). "For instance, we detected key actionable mutations, such as KRAS G12C and EGFR T790M, exclusively in plasma in certain stage III cases, underscoring the importance of combining liquid biopsy with tissue biopsy for more comprehensive lung cancer management." (PMID 40282516, 2025). "In in vivo models, we demonstrated that KRAS G12C inhibitors in combination with the FGFR inhibitor pemigatinib was most efficacious compared to single-agent treatment in the LU99 mesenchymal lung cancer model, which was correlated to increased inhibition of pERK in the combination group." (PMID 40788860, 2025).
lung cancer (continued). "Heterogeneity and biological plasticity are typical features of tumours, which limit the initial therapy response rate and allow for the early adaptation to clinical treatment, thereby representing a critical challenge of curation in various cancer types, including KRAS‐mutant lung cancer." (PMID 41025426, 2025). "To rigorously investigate whether KRAS mutations confer platinum resistance in lung cancer cells, we adopted 2 approaches: overexpressing a constitutively active KRAS mutant in NCI-H522 (KRAS WT) and knocking down KRAS in NCI-H23 (KRAS G12C) cells." (PMID 39960727, 2025). "In summary, loss of LKB1 significantly contributes to the immune-cold phenotype observed in NSCLC and may collaborate with KRAS through multiple mechanisms during lung cancer pathogenesis." (PMID 40429821, 2025). "We also showed Lac synergized with PD-1 inhibitors to shrink lung cancers driven by mutant KRAS." (PMID 39979425, 2025). "Its tumor-suppressive role has been confirmed in KRAS-mutant cells and lung cancer models." (PMID 40260417, 2025). "Radiomics demonstrates high potential value in predicting the KRAS status in lung cancer." (PMID 41584578, 2025). "Moreover, qRT-PCR analyses showed that both the DDB2 and XPC genes were expressed at much higher levels in primary KRAS-mutant lung cancer cells compared with primary KRAS WT lung cancer cells." (PMID 39960727, 2025). "Nonetheless, our findings with WEE1 inhibitors and Sotorasib suggest WEE1 inhibitors may enhance the efficacy of KRAS-targeted therapies, improving clinical outcomes in KRAS-mutant lung cancer." (PMID 40885709, 2025). "Moreover, cells with the presence of the WT KRAS allele together with mutant KRAS were sensitive towards the FoxM1 inhibitor siomycin, suggesting that the targeting of FoxM1 could be a therapeutic approach in the treatment of lung cancer with both the WT and mutant KRAS alleles." (PMID 41294676, 2025). "Furthermore, CRAF suppression is synthetic lethal with MEK inhibition in KRAS-mutant colorectal as well as in lung cancer cells, and prolonged suppression of ERK signaling is achieved by dual blockade of RAF and MEK." (PMID 41023593, 2025). "Our findings suggest that the dual inhibition strategy may offer a promising and tolerable combinatorial strategy for KRAS G12C-mutant lung cancer." (PMID 40885709, 2025). "In a KRAS-G12D-induced lung cancer model, dual inhibition significantly delayed tumor progression." (PMID 40335986, 2025). "Moreover, we generated DDX3X-knock down cells in a KRAS mutant human lung cancer cell A549 (KRASG12S) and found suppression of DDX3X halted the proliferation of A549 cells." (PMID 40885716, 2025). "However, resistance to KRAS inhibitors when used alone has been reported in several cancers other than lung cancer, highlighting the urgency to discover effective drugs for combination therapy." (PMID 39400496, 2025). "In lung cancer, KRAS-mutant tumors were found to upregulate Tregs through IL-6 signaling." (PMID 40524071, 2025). "The downregulation of KRAS signaling was also observable in other cancer cell lines carrying different KRAS mutations, including the pancreatic cancer cell line Capan-2 (KRASG12V), and the lung cancer cell lines H23 (KRASG12C) and A549 (KRASG12S)." (PMID 40473213, 2025). "Consistent with the requirement for MAPK signaling in KRAS-driven lung cancer, these findings suggest that Kras allelic imbalance may further promote MAPK pathway activity and tumor growth." (PMID 41219537, 2025). "In the KRAS G12C-mutated H358 lung cancer cell line, LY3537982 exhibited significantly lower IC50 values for the inhibition of GTP-bound KRAS and phosphorylated ERK than the other two KRAS G12C inhibitors, underscoring its potent tumor growth inhibition effect." (PMID 40303413, 2025).
lung cancer (continued). "By integrating structural bioinformatics with molecular and expression data, this study aims to reinforce the role of EGFR, ALK, KRAS, and PD-1 as precision targets in lung cancer, providing a foundation for future diagnostics, therapeutic design, and personalized oncology strategies." (PMID 40927719, 2025). "In summary, resistance to KRAS inhibitors is anticipated with their increased clinical use, and the mechanisms of resistance need to be understood to provide long-term benefits for lung cancer patients." (PMID 39782689, 2025). "Such scenarios relate to biomarkers and testing in lung cancer, small cell lung cancer, EGFR mutations and targeted therapy in non-small cell lung cancer (NSCLC), early-stage NSCLC, KRAS/BRAF/MET and other genomic alterations in NSCLC, and immunotherapy in advanced NSCLC." (PMID 39237103, 2025). "In addition, Lac synergizes with PD-1 inhibitor to shrink lung cancers driven by mutant KRAS in a mouse model." (PMID 39979425, 2025). "Notably, NER activity was significantly higher in KRAS-mutant NSCLC cells compared with KRAS WT lung cancer cells, suggesting a positive correlation between KRAS mutations and NER activity in NSCLC cells." (PMID 39960727, 2025). "m6A-seq analysis suggests that the constitutively active KRAS mutant overexpression led to an m6A increase in the genes associated with NER, suggesting an important role of the NER pathway in KRAS-mutant–mediated platinum resistance in lung cancer cells." (PMID 39960727, 2025). "While antioxidants may slow tumor progression in specific cancers such as MYC-driven lymphoma, they can accelerate tumor growth, metastasis, and angiogenesis in other settings, including KRAS-driven lung cancer and BRAF-driven melanoma." (PMID 40646353, 2025). "In summary, our results suggest that the combination of G12C inhibitors with FGFR inhibitors such as pemigatinib may improve clinical outcomes in patients with mesenchymal-like lung cancer and KRAS G12C." (PMID 40788860, 2025). "Interestingly, the IC50 of 7T_PDO treated with adagrasib was significantly higher than that of KRAS p.G12C-mutant lung cancer cell lines, at 39.21 μM vs. 0.8954 μM, respectively." (PMID 41315187, 2025). "For example, in non–small cell lung cancer (NSCLC) tissue and/or circulating tumor DNA, STK11 and KRAS alterations frequently occur together, and STK11 variants, especially when coupled with pathogenic KRAS variants, can lead to resistance against immunotherapy in these cancers." (PMID 40860288, 2025). "Additionally, genes involved in the MAPK signaling pathway include BRAF, c-Jun, ERK, JNK, MAP2K1, MAP2K4, MAPK14, and KRAS, which are genes affected by MPs in lung cancer cells." (PMID 41378310, 2025). "Thus, there is a large unmet need to optimize immunotherapy strategies in KRAS-mutant lung cancer to improve patient outcomes." (PMID 40486486, 2025). "Subsequently, we examined DPP4 expression in KRAS-mutant lung cancer cell lines." (PMID 41283988, 2025). "Indeed, EVs have been shown to deliver KRAS siRNA to inhibit the growth of lung cancer, while the transfer of anti-miR21 oligonucleotides via modified EVs has been found to suppress tumor growth in glioblastoma." (PMID 40611320, 2025). "Interestingly, knockdown of either ETV4 or ETV5 strongly inhibited the growth of human KRAS-mutant lung cancer cell lines, suggesting that the requirement for these transcription factors extends to human lung cancer." (PMID 41219537, 2025). "We reported previously that silencing LDHB in KRAS-mutant lung cancer cell lines significantly reduced the expression of SLC7A1111, which is required for oncogenic RAS transformation and encodes a plasma membrane-localized cystine/glutamate antiporter that provides cysteine for GSH synthesis." (PMID 40090955, 2025). "In our previous research, we reported that the “open conformation” on the surface of HRASG60A‐GppNp might be a potential target for KRAS‐driven non‐small cell lung cancer therapy." (PMID 40390765, 2025).
lung cancer (continued). "The combination of Sot and histone deacetyltransferase inhibitors could be an effective treatment for KRAS-mutant lung cancer." (PMID 41475546, 2025). "Glecirasib also showed strong antitumor efficacy in the LUN156 (KRAS p.G12C) lung cancer PDX model." (PMID 40304209, 2025). "Our previous study found that MED23 could selectively support the cell growth and tumorigenesis of lung cancer cell lines with mutant KRAS in vitro." (PMID 38195889, 2024). "However, two direct inhibitors of KRAS, sotorasib and adagrasib, have recently been identified as reliable and promising for treating patients with metastatic KRAS-positive lung cancer." (PMID 39199653, 2024). "Recently, in the setting of lung cancer, advances in RAS variant-specific targeting have been achieved with FDA approval of sotorasib and adagrasib in patients with locally advanced or metastatic non-small cell lung cancer harboring a KRAS p.Gly12Cys variant." (PMID 39309743, 2024). "Although KRAS mutations are detectable in a high proportion of PDACs, almost in half of colorectal adenocarcinomas (CRC) and in approximately 30% of lung adenocarcinomas, higher response rates for KRAS-targeted therapy are so far restricted to lung cancer." (PMID 38686056, 2024). "Notably, KRAS G12F lung cancer models have reduced sensitivity to G12C‐specific inhibitors in vitro compared with KRAS G12C lung cancer cell lines." (PMID 38572952, 2024). "To investigate the link between KRAS-mutant variants and HOXC10 expression, we obtained spine metastatic tissue with KRAS mutations including G12V/S and Q61H that mutation commonly occur in human lung cancer." (PMID 39191757, 2024). "Our study suggests that dual silencing of PD-L1 and KRAS by CRISPR/Cas9 may be a promising therapeutic approach for the treatment of lung cancer." (PMID 39201772, 2024). "Comparable results were seen in other KRAS-Q61H lung cancer cell lines in a separate study." (PMID 39372214, 2024). "MEK inhibitor resistance enables KRAS-mutant lung cancer cells to bypass canonical KRAS effectors." (PMID 39501277, 2024). "Similarly, in a study, lung cancer patients harboring KRAS mutant tumors with high UHRF1 expression had poorer prognosis." (PMID 39051184, 2024). "Indeed, KRAS inhibition has been clinically achieved in lung cancer and, at the pre-clinical level, in pancreatic cancer as well." (PMID 38607041, 2024). "We next evaluated whether activated HOXC10 coordinated with oncogenic KRAS and played a promoting role in bone metastasis of lung cancer development." (PMID 39191757, 2024). "Our results showed that the cell growth inhibition rates of the HOXC10 inhibition reached 53.2%–85.3% compared to those of the empty vector group of KRAS-mutant lung cancer bone metastasis cells, according to colony formation, CCK8, LDH release, and EDU assays." (PMID 39191757, 2024). "Understanding the exact molecular mechanisms through which KRAS mutations influence CBX3 function, and vice versa, could open new avenues for targeted therapies in lung cancer patients harboring these mutations." (PMID 39272883, 2024). "MicroRNA-31 promotes lung tumorigenesis, especially in mutant KRAS-driven lung cancer." (PMID 38836056, 2024). "Collectively, data obtained using allografts, orthotopic transplantation and genetically-engineered KRAS-driven lung cancer mouse models clearly demonstrate that transient OSKM expression impairs tumor initiation and progression and results in a significant reduction of the tumor burden." (PMID 39587064, 2024). "Consistent with this, increased expression levels of SLC7A5 have been observed in various types of cancer such as breast cancer, KRAS-mutated CRC, gastric cancer, lung cancer, pancreatic cancer, prostate cancer, melanoma, ovarian cancer and hepatocellular carcinomas, and esophageal cancer." (PMID 38459595, 2024).
lung cancer (continued). "In addition to CRC, KRAS mutations are implicated in various other cancers, including pancreatic cancer (PDAC), lung cancer, and certain subtypes of ovarian and endometrial cancers." (PMID 39456549, 2024). "While previous research has established the significance of KRAS mutations in lung cancer development and progression, there remains a lack of clarity regarding the specific types and consequences of these mutations." (PMID 38374309, 2024). "An activating KRAS mutation was discovered in human lung cancer samples in 1984, which were absent in the corresponding normal tissue." (PMID 38374309, 2024). "Moreover, a separate subheading focusing on SMARCA4 and KRAS co-mutation survival outcomes in patients with NSCLC is included, as this has recently become a medically relevant topic in the lung cancer community." (PMID 39063938, 2024). "Similarly, we tested an immunocompetent, syngeneic model of KRASG12C mutant lung cancer using 3LL ΔNRAS cells, a variant of Lewis lung carcinoma that harbors an endogenous KRASG12C mutation and responds to KRAS inhibitors." (PMID 38483480, 2024). "In closing, our data support the testing of ULK1/2 inhibitors in patients with KRAS-driven lung cancer, either as single agents or in combination with direct inhibitors of KRAS oncoproteins, or of KRAS-regulated signaling pathways downstream of KRAS such as the RAF>MEK>ERK MAP kinase pathway." (PMID 39213022, 2024). "Also, a previous study demonstrated that the KL lung cancer model showed high levels of collagen deposition compared to KRAS-only model." (PMID 38291516, 2024). "Notably, a regimen of dual inhibition of HOXC10 and STAT3 is established to improve the effectiveness of HOXC10 inhibition alone in KRAS-mutant lung cancer bone metastasis." (PMID 39191757, 2024). "Last but not least, KRAS mutated lung cancer cells also modulate ACSL3 expression to remodel fatty acid metabolism and to increase the content of MUFA-PLs." (PMID 38908072, 2024). "Patients with mutations such as KRAS, BRAF and c-MET may benefit from NA ICI-chemo based on the extrapolation of the benefit of immunotherapy in patients with advanced lung cancer who have these mutations." (PMID 38610980, 2024). "Also, regarding the importance of SLC3A2-NRG1 fusion in lung cancer, in another study, it was shown that KRAS enhances tumor growth in SLC3A2-NRG1–positive lung cancer cells through ADAM17-mediated NRG1 cleavage." (PMID 38705513, 2024). "Recently, we could show that the co-mutations of KRAS + KEAP1, STK11 + KEAP1 and KRAS + STK11 + KEAP1 lead to a significantly shorter median overall survival (mOS) in patients with lung cancer across treatments by analyzing multiple dataset." (PMID 39156705, 2024). "CBX3 has a significant effect on the KRAS signaling pathway in lung cancer." (PMID 39272883, 2024). "As an alternative approach, a greater understanding of the mechanisms by which oncogenic KRAS drives immune evasion may identify novel immunotherapy combination strategies that could improve outcomes for patients with KRAS-mutant lung cancer." (PMID 38635884, 2024). "Interestingly, ACSL3 has also been proposed as a pharmacological target for mutant KRAS lung cancer, pancreatic cancer, clear cell renal cell carcinoma, and colorectal carcinoma." (PMID 38879607, 2024). "Notably, ERK5 has been already found upregulated in KRAS-lung cancer, additionally supporting the need to target it." (PMID 39271958, 2024).